RN7SL210P (RNA, 7SL, cytoplasmic 210, pseudogene)
Gene: Miscellaneous RNA gene on chromosome 2 (96,004,563 to 96,004,850, reverse strand). Ensembl gene ENSG00000275961.
Homologues: Orthologues: chimpanzee Metazoa_SRP (99% identical), macaque Metazoa_SRP (75% identical). Paralogues in human: RN7SL313P (96% identical), RN7SL1 (85% identical), RN7SL566P (85% identical), RN7SL2 (84% identical), RN7SL3 (83% identical), RN7SL45P (83% identical), RN7SL296P (83% identical), RN7SL113P (82% identical), RN7SL597P (82% identical), RN7SL186P (81% identical), RN7SL230P (81% identical), RN7SL278P (81% identical), and 704 more.